PVALB (parvalbumin)
Diseases named in the same sentence as PVALB in open-access papers (continued):
Sharing a sentence is not in itself a finding about the gene and the disease.
fragile X syndrome (5 papers, 2017 to 2025). A genetic syndrome caused by mutations in the FMR1 gene which is responsible for the expression of the fragile X mental retardation 1 protein. "Fragile X syndrome (FXS) results from loss of FMR1-encoded FMRP and is associated with reduced density of parvalbumin (PV) neurons; however, the mechanism underlying this abnormality remains unknown." (PMID 40672286, 2025).
Obesity (5 papers, 2022 to 2025). Accumulation of substantial excess body fat. "Additional mechanisms underlying a shift in GABAergic function with diet induced obesity include regulation of parvalbumin (PV)-containing interneurons either directly or through changes to the perineuronal net (PNN) surrounding these neurons." (PMID 37793910, 2023). "In our study, the MQ group exhibited restored expression of HFD‐dysregulated genes (Runx3 and parvalbumin) while concurrently counteracting HFD‐induced obesity." (PMID 41306337, 2025). "Taken together, this study implicates parvalbumin as a potential therapeutic strategy against obesity, which will need further evaluation in humans." (PMID 35676256, 2022). "Here the authors profile serum proteomics in exercised mice to find reduced parvalbumin levels that correlate with increased M2 macrophage and suppressed diet-induced obesity to hint parvalbumin as a potential therapy target against obesity." (PMID 35676256, 2022). "Thus, our data indicate that serum level of parvalbumin correlates with both mouse and human obesity." (PMID 35676256, 2022). "More importantly, serum concentrations of parvalbumin positively correlate with obesity in mouse and human, while treating mice with a recombinant parvalbumin blocker prevents its interaction with CSF1R and promotes M2 macrophage polarization and ameliorates diet-induced obesity." (PMID 35676256, 2022). "Thus, although further studies are required to assess the significance of parvalbumin in mediating the effects of exercise, our results implicate parvalbumin as a potential therapeutic strategy against obesity in mice." (PMID 35676256, 2022). "Our data indicate that parvalbumin blocker might represent a valuable therapeutic approach for anti-obesity and prompt us to evaluate its effect on obesity." (PMID 35676256, 2022). "However, whether parvalbumin secretion from muscle is altered by exercise in humans and its functional relevance to human obesity will need further evaluation." (PMID 35676256, 2022). "We next explored whether serum level of parvalbumin correlates with mouse and human obesity." (PMID 35676256, 2022). "Despite the difference in parvalbumin expression in mice and humans, we were able to prove that parvalbumin suppressed M2 macrophage polarization in both mice and humans, thus targeting parvalbumin may serve as a strategy to combat against obesity in humans, which will need further evaluation." (PMID 35676256, 2022). "Most Importantly, blocker that blocks parvalbumin and CSF1R interaction not only rescued M2 macrophage activation, insulin sensitivity and thermogenesis but also ameliorated obesity in mice." (PMID 35676256, 2022). "Indeed, serum levels of parvalbumin were dramatically elevated in HFD-fed mice compared with RD-fed mice, indicating its correlation with obesity." (PMID 35676256, 2022). "Moreover, targeting parvalbumin by a synthetic blocker that blocks the interaction between parvalbumin and colony stimulating factor 1 receptor (CSF1R) ameliorates diet-induced obesity in mice." (PMID 35676256, 2022). "Although we reported an upregulation of circulating levels of parvalbumin, which correlated with human obesity, we could not conclude that the upregulation of parvalbumin in the serum was mediated by muscle secretion." (PMID 35676256, 2022).
Sepsis (5 papers, 2015 to 2025). Sepsis is defined as life-threatening organ dysfunction caused by a dysregulated host response to infection. "Additionally, mouse models of sepsis have lower levels of glutamatergic NMDA receptors, as well as reduced numbers of doublecortin-positive newborn neurons and parvalbumin interneurons in the hippocampus." (PMID 31920505, 2019).
Tinnitus (5 papers, 2017 to 2024). Tinnitus is an auditory perception that can be described as the experience of sound, in the ear or in the head, in the absence of external acoustic stimulation. "Loss of parvalbumin-positive interneuron activity is involved in the development of tinnitus." (PMID 37736859, 2023). "Parvalbumin interneurons are also discussed as key players in the context of the manifestation of tinnitus." (PMID 39062188, 2024). "Pathological alterations in parvalbumin-positive interneurons and somatostatin-positive interneurons as well as subsequent multiple excitatory-inhibitory neural interactions may lead to the emergence and maintenance of tinnitus perception." (PMID 28053240, 2017). "c-Fos staining revealed that parvalbumin (PV)-positive neurons showed no significant activation in the tinnitus group compared to the nontinnitus and control groups." (PMID 39296986, 2024).
Alpers syndrome (4 papers, 2019 to 2025). A cerebral degeneration that results in progressive degeneration of grey matter in the cerebrum and has_symptom convulsions. "This suggests that parvalbumin + interneuron loss in the visual cortex is selectively accompanied by reactive astrogliosis in Alpers’ syndrome." (PMID 37259148, 2023). "Quantification of mean optical intensities revealed a high proportion of parvalbumin+ interneurons from all patients with Alpers' syndrome had combined severe NDUFB8 and COXI deficiencies." (PMID 35790454, 2022). "Cortical neuronal loss within occipital cortex tissues from patients with Alpers' syndrome involved a marked loss of a number of cell types, of which parvalbumin+ interneurons were the most severely affected." (PMID 35790454, 2022). "Quantification revealed a significant loss of parvalbumin+ interneurons within the occipital cortex of patients with Alpers' syndrome relative to controls and SUDEP patients (P < 0.001) including a severe loss in 8 of 10 patients (z < −4)." (PMID 35790454, 2022). "Since there was a consistent, severe loss of parvalbumin+ interneurons in Alpers' syndrome, immunofluorescence was used to interrogate OXPHOS protein expression in these cells to provide further insight into the aetiology of this interneuron vulnerability." (PMID 35790454, 2022). "Furthermore, all patients with Alpers' syndrome showed more severe COXI deficiencies within parvalbumin+ interneurons relative to calretinin+ interneurons in the frontal cortex (Mann–Whitney, P < 0.0001)." (PMID 35790454, 2022). "Interestingly, parvalbumin+ interneurons frequently showed a greater loss of complex IV subunits relative to complex I subunits, particularly within the younger Alpers' syndrome patients." (PMID 35790454, 2022). "Interestingly, parvalbumin+ interneurons from patients with Alpers' syndrome showed a trend towards greater loss of COXI protein expression relative to NDUFB8." (PMID 35790454, 2022). "Since parvalbumin+ interneuron loss was extensive in Alpers' syndrome patient tissues, the severe loss of complex IV subunits may be more detrimental to the functioning and survival of parvalbumin+ interneurons." (PMID 35790454, 2022). "In addition to the consistent loss of parvalbumin+ interneurons and overall preservation of calretinin+ interneurons in Alpers' syndrome, we demonstrated differential OXPHOS deficiency profiles within these two interneuron subtypes." (PMID 35790454, 2022). "Our neuropathological study has revealed an increased vulnerability of parvalbumin‐positive inhibitory interneurons to dysfunction and degeneration in Alpers' syndrome which likely underlies the severe occipital‐predominant epilepsy in patients with Alpers' syndrome." (PMID 35790454, 2022). "The nonfast spiking activity of calretinin+ interneurons is likely to be associated with reduced metabolic requirements compared with parvalbumin+ interneurons, which may underlie the increased resilience of calretinin+ interneurons to mitochondrial dysfunction in Alpers' syndrome." (PMID 35790454, 2022). "Furthermore, we have demonstrated enrichment of parvalbumin+ interneurons in the occipital cortex which, combined with their apparent increased vulnerability, suggests that this underlies the occipital focus of seizures in Alpers' syndrome." (PMID 35790454, 2022). "This novel finding suggests a more severe involvement of complex IV in parvalbumin+ interneuron dysfunction in Alpers' syndrome." (PMID 35790454, 2022). "This highlights the critical dependence of OXPHOS for optimal function of parvalbumin+ interneurons and implicates an increased vulnerability of these interneurons in Alpers' syndrome where OXPHOS function is severely impaired." (PMID 35790454, 2022).
Alpers syndrome (continued). "The levels of NDUFB8 and COXI deficiencies within calretinin+ interneurons were significantly less severe when compared with parvalbumin+ interneurons in the occipital and temporal cortices of almost all patients with Alpers' syndrome (Mann–Whitney, P < 0.05)." (PMID 35790454, 2022). "This suggests a consistent severe dysfunction of parvalbumin+ interneurons relative to calretinin+ interneurons in Alpers' syndrome, even in tissues affected by severe neuronal necrosis." (PMID 35790454, 2022). "At the group level, parvalbumin+ interneuron densities were also significantly reduced in the frontal cortex (P < 0.001) and temporal cortex (P < 0.05) of patients with Alpers' syndrome relative to controls." (PMID 35790454, 2022). "An apparent vulnerability of parvalbumin+ interneurons in Alpers' syndrome is perhaps an unsurprising finding due to the well‐recognised dependence of parvalbumin+ interneurons on functioning mitochondria." (PMID 35790454, 2022). "This study aimed to determine whether specific interneuron subtypes are differentially affected in Alpers' syndrome, with a particular focus on parvalbumin+ interneurons." (PMID 35790454, 2022). "Alpers' syndrome patient parvalbumin+ interneurons show reduced levels of parvalbumin+ protein expression relative to control interneurons which may be indicative of reduced calcium‐binding capacity." (PMID 35790454, 2022). "This may suggest that there is a preferential impairment of complex IV within parvalbumin+ interneurons in Alpers' syndrome." (PMID 35790454, 2022). "Alpers' syndrome patients also showed a consistent increase in mitochondrial mass within parvalbumin+ interneurons of the occipital cortex which may represent a compensatory response to severe OXPHOS deficiencies." (PMID 35790454, 2022). "Since parvalbumin expression is activity‐regulated, this may suggest reduced activity of parvalbumin+ interneurons in Alpers' syndrome." (PMID 35790454, 2022). "We hypothesised that parvalbumin‐positive(+) interneurons, a neuronal class critical for inhibitory regulation of physiological cortical rhythms, would be particularly vulnerable in Alpers' syndrome due to the excessive energy demands necessary to sustain their fast‐spiking activity." (PMID 35790454, 2022). "A lower expression of parvalbumin was detected within Purkinje neurons in the late-POLG and mtDNA disease groups (P = 0.0139); however, parvalbumin expression was unaltered at the Alpers’ syndrome patient group level (P = 0.0564)." (PMID 40445405, 2025). "A loss of parvalbumin+ protein expression and altered mitochondrial mass has been reported in ASD, suggesting that overlapping mechanisms may mediate parvalbumin+ interneuron dysfunction in ASD and Alpers' syndrome." (PMID 35790454, 2022).
amyotrophic lateral sclerosis (4 papers, 2021 to 2023). Amyotrophic lateral sclerosis (ALS) is a neurodegenerative disease characterized by progressive muscular paralysis reflecting degeneration of motor neurons in the primary motor cortex, corticospinal tracts, brainstem and spinal cord. "MIF and PVALB are associated with amyotrophic lateral sclerosis, a neurodegenerative disease targeting motor neurons." (PMID 34763096, 2022). "Finally, analysis of human post-mortem brains confirmed a paucity of parvalbumin interneurons in the prefrontal cortex in sporadic amyotrophic lateral sclerosis and amyotrophic lateral sclerosis linked to C9orf72 mutations." (PMID 34136812, 2021). "Parvalbumin neuron density was quantified in post-mortem amyotrophic lateral sclerosis frontal cortex." (PMID 34136812, 2021). "They confirm reduced parvalbumin interneurons in human amyotrophic lateral sclerosis." (PMID 34136812, 2021).
Hearing impairment (4 papers, 2012 to 2025). A decreased magnitude of the sensory perception of sound. "This possibility is consistent with the fact that congenital deafness has been shown to prevent the maturation of GABAergic transmission in the auditory cortex, and sensory hearing loss has been associated with a decrease in the number of parvalbumin-positive cells in the superior olivary complex." (PMID 23055939, 2012). "Density of parvalbumin-immunoreactive inhibitory interneurons in the auditory cortex was abnormally low in Df1/+ mice with hearing impairment, and gain of click-evoked cortical AEPs was abnormally high." (PMID 39779687, 2025).
amyloidosis (3 papers, 2020 to 2021). A disorder characterized by the localized or diffuse accumulation of amyloid protein in various anatomic sites. "Here, we show that amyloid-beta-induced hyperexcitability of hippocampal inhibitory parvalbumin (PV) interneurons importantly contributes to neuronal network dysfunction and memory impairment in APP/PS1 mice, a mouse model of increased amyloidosis." (PMID 31431685, 2020).
breast carcinoma (3 papers, 2020 to 2021). "In contrast, tumors with an hPRLrIlo/hPRLrLhi ratio were enriched in genes associated with luminal breast cancer (e.g., CGA, PVALB, NOVA1), and were more likely to be small in size and early stage." (PMID 33772010, 2021).
neuroblastoma (3 papers, 2012 to 2026). Neuroblastoma (NB) is the most common solid, extracranial childhood tumor. "Using q-RT-PCR in cerebellar homogenates from PGC-1α−/− mice, we measured expression of 37 microarray-identified transcripts upregulated by PGC-1α in SH-SY5Y neuroblastoma cells with neuroanatomical overlap with PGC-1α or parvalbumin (PV), a calcium buffer highly expressed by Purkinje cells." (PMID 25610371, 2014). "PVALB has previously been identified as a main target gene of PGC-1α: in PGC-1α knockout mice, a marked reduction of PVALB mRNA levels was observed in the cerebrum, retina and heart; conversely a robust increase was detected after PGC-1α overexpression in neuroblastoma cells." (PMID 22272266, 2012).
prion disease (3 papers, 2010 to 2024). A transmissible disease that is caused by a protein that is able to induce abnormal folding of normal cellular proteins, leading to characteristic spongiform brain changes, which are associated with neuronal loss without an inflammatory response. "Severe loss of parvalbumin-positive neurons is also observed in human transmissible spongiform encephalopathies (TSEs), prion diseases." (PMID 20678225, 2010). "In previous studies, GABAergic parvalbumin-positive (PV+) neurons were identified as the most vulnerable in prion diseases." (PMID 39361421, 2024). "However, studies in ME7 prion disease revealed no significant loss of parvalbumin (PV)-positive GABAergic inhibitory neurons in the hippocampus of ME7-animals." (PMID 25623034, 2015).
Rett syndrome (3 papers, 2018 to 2023). A severe neurodevelopmental disorder affecting the central nervous system. "In line, excessive hyperpolarization by axosomatic parvalbumin-positive interneurons has been implicated in the stunted dendritic growth typical for Rett syndrome." (PMID 37587917, 2023).
tetanus (3 papers, 2021 to 2023). A serious infectious disorder that follows wound contamination by the Gram-positive bacterium Clostridium tetani. "During a tetanus, the Mg2+ is replaced by Ca2+, and the slow release of Ca2+ from parvalbumin would maintain [Ca2+] above its resting level on the timescale of seconds after the tetanus." (PMID 34121660, 2021). "One possible explanation for the slowing of Ca2+ decay could be the slow binding to parvalbumin following Mg2+ dissociation during prolonged tetanus, but this line of inquiry was not pursued further." (PMID 37474311, 2023).
Ataxia (2 papers, 2017 to 2024). Ataxia refers to impaired coordination of voluntary muscle movement. "Finally, deletion of calcium buffering proteins like calbindin-28K or parvalbumin cause ataxia and deletion of one copy of calbindin-28K accelerates the ataxia phenotype in SCA1 mice." (PMID 28518055, 2017).
food allergies (2 papers, 2022 to 2023). "More than 95% of all fish-induced food allergies are caused by PVALB proteins." (PMID 36672964, 2023). "Research has shown that iodine-rich food allergy (i.e., seafood allergy) is not caused by iodine itself; instead, it is caused by other proteins including tropomyosin and parvalbumin in shellfish and fish, respectively." (PMID 35833013, 2022).
glaucoma (2 papers, 2022 to 2023). Increased pressure in the eyeball due to obstruction of the outflow of aqueous humor. "Microarray analysis of the retinal gene expression in the DBA/2J mice at different ages showed that the expression of PVALB was downregulated as the mice aged and developed glaucoma with retinal ganglion cell loss." (PMID 37901418, 2023). "In the present study, we have identified PVALB as an effective marker with which to track RGC loss in both glaucoma animal model of disease and wide-used optic nerve injury model." (PMID 37901418, 2023). "Moreover, an overall reduction in parvalbumin expression in the retina was also shown in diabetic retinopathy and glaucoma, suggesting the possible selective loss of parvalbumin-positive neurons." (PMID 35629305, 2022). "However, as the mice aged and developed glaucoma, the PVALB transcript levels showed a reduction from 8-month-old to 12-month-old mice (p < 0.0001, n = 20; unpaired t-test)." (PMID 37901418, 2023). "Changes in PVALB expression have not been previously studied in the DBA/2J mouse genetic model of glaucoma." (PMID 37901418, 2023).
glioma (2 papers, 2021). A benign or malignant brain and spinal cord tumor that arises from glial cells (astrocytes, oligodendrocytes, ependymal cells). "Interestingly, it has been demonstrated that the selective optogenetic stimulation of parvalbumin-positive GABAA interneurons induces a significant reduction in glioma cell proliferation." (PMID 34512501, 2021). "In the latest years it has been demonstrated that, while pyramidal cell activity promotes proliferation in both murine and patient-derived high-grade gliomas, the selective stimulation of parvalbumin-positive interneurons elicits the opposite effect in glioma-bearing mice." (PMID 34690699, 2021).
memory impairment (2 papers, 2021 to 2023). "Conversely, partial depletion of parvalbumin neurons in neonates was sufficient to engender long-lasting memory impairment." (PMID 36394958, 2023).
peripheral nerve injury (2 papers, 2022 to 2024). Injury to a peripheral nerve. "For example, parvalbumin (Pvalb), a calcium binding protein that identifies a subpopulation of proprioceptive DRG neurons and has been shown to be associated with peripheral nerve injury, is found to be significantly decreased by paclitaxel." (PMID 38979383, 2024).